INS (insulin)
Diseases named in the same sentence as INS in open-access papers (continued):
Sharing a sentence is not in itself a finding about the gene and the disease.
Obesity (continued). "Consistent clustering was also observed between BMI and METS-IR (r = 0.84), as well as with BRI (r = 0.82) and AVI (r = 0.78), affirming obesity’s close ties to insulin resistance and abdominal geometry in this group." (PMID 41465784, 2025). "There are many obesity-related hormones; however, only the key hormones, insulin, leptin, and adiponectin, were measured." (PMID 40431382, 2025). "Remarkably, insulin secretion stimulated by exendin-4 was also decreased, suggesting that obesity increases β-cells sensitivity to myeloid Gq-related suppression, even with GLP-1 receptor activation." (PMID 41278909, 2025). "The weights of the pancreas, liver, skeletal muscles, and brain were assessed as these organs play important roles in the regulation of insulin sensitivity and glucose homeostasis and their function can be affected by obesity and fat accumulation." (PMID 41514930, 2025). "Histidine is an essential amino acid that has been demonstrated to have antioxidant properties, reduce inflammatory burden, and reduce oxidative stress, and it is closely related to insulin sensitivity, obesity, and MS." (PMID 40438394, 2025). "High EPO expression in skeletal muscle, achieved via gene transfer in mice, protected against obesity, reduced fat mass and body weight, and normalized glucose tolerance and fasting insulin levels in high-fat diet-fed mice." (PMID 39996752, 2025). "The estimated oxidation rates of the dietary fatty acid, palmitate, were 1.4 times higher in young children with overweight/obesity who were insulin sensitive, compared to children with normal weight who were insulin sensitive." (PMID 40525760, 2025). "Our study identifies Htr2b as a novel regulator of skeletal muscle insulin sensitivity and highlighted the therapeutic potential of targeting skeletal muscle 5-HT signaling in the treatment of obesity-related metabolic diseases." (PMID 40451926, 2025). "In adults with obesity, interrupting sitting about every ≤30 min with 2–5 min of light-to-moderate walking or simple resistance acutely attenuates postprandial glucose and insulin responses." (PMID 41356824, 2025). "It is also challenging to differentiate PCOS-specific changes from the obesity-induced alterations in insulin sensitivity for the ∼61% of PCOS patients who are also overweight or obese." (PMID 40013621, 2025). "Its potential in mitigating obesity is evidenced by improvements in insulin sensitivity, adiposity reduction, and body weight regulation." (PMID 39967592, 2025). "Oral glutamine supplementation reduces obesity, and pro-inflammatory markers, improves insulin sensitivity in rats, and reduces waist circumference in overweight and obese human." (PMID 40649995, 2025). "More studies are needed to tease apart the role of pre-existing metabolic syndrome and obesity in the insulin-activated T cell mechanism of lymphedema." (PMID 40821816, 2025). "Obesity contributes to excess adiposity, which reduces adiponectin and increases pro-inflammatory factors, thereby disrupting insulin signaling." (PMID 41302116, 2025). "Specifically, we explore its impact on hunger regulation, glycaemic control, insulin sensitivity, inflammation, psychological well-being, and the reduced need for obesity medications." (PMID 40289934, 2025). "The Lira Pump trial evaluated liraglutide (1.8 mg daily) as an adjunct in individuals with T1DM and overweight or obesity on insulin pumps and poor glycemic control." (PMID 40707821, 2025). "Here we show that tissue-specific knockout of histone chaperone HIRA in mice impairs insulin sensitivity and alleviates adipose tissue expansion during high-fat diet-induced obesity, but only moderately affects embryonic development of adipose tissue." (PMID 40196683, 2025). "Subgroup analyses indicated that supplementation with high-dose, long-duration purified hesperidin, particularly in individuals with metabolic disorders and obesity, had a positive effect on insulin levels." (PMID 41586243, 2025).
Obesity (continued). "Taken together, these results suggested that EC significantly improved the glucose tolerance and insulin sensitivity of obesity mice." (PMID 41464979, 2025). "The “Carbohydrate-Insulin Model” of obesity proposes that consuming large amounts of processed carbohydrates triggers hormonal changes, particularly increased insulin secretion, which promotes fat storage, increases hunger, and reduces energy expenditure." (PMID 40944293, 2025). "Obesity induces an aberration of circulating factors (e.g., insulin, growth hormones, IGF-1, androgens, and pro-inflammatory cytokines), which, in addition to reduced physical activity, impact protein synthesis and degradation." (PMID 40610657, 2025). "Nine individuals with obesity and T2D had their peripheral insulin sensitivity and β-cell function evaluated before and one month after biliopancreatic diversion using minimal model analysis and either intravenous (IVGTT) or OGTT tests." (PMID 41155711, 2025). "The substrate profile resembles Magl, the major 2-arachidonoyl glycerol (2-AG) hydrolase, which plays a role in glucose-stimulated insulin secretion, obesity prevention, and development of metabolic syndromes." (PMID 39657853, 2025). "Beyond blood pressure reduction, the DASH diet also helps reduce the risk of overweight and obesity, lower total and LDL cholesterol levels, and regulate glucose and insulin imbalances." (PMID 40699839, 2025). "Adipose‐specific knockout of MTCH2 protected against diet‐induced obesity and metabolic disorders, as evidenced by reduced fat deposition in adipose tissues and the liver, along with improved insulin sensitivity." (PMID 40051328, 2025). "This improved insulin sensitivity and increased energy expenditure in these mice, protecting them from diet-induced obesity." (PMID 41115589, 2025). "Considering the patient's significant obesity and preserved insulin secretion, this case should rather be diagnosed as SPIDDM (probable) and should be followed up while assessing the degree of insulin secretion ability." (PMID 40226121, 2025). "In heart failure with preserved ejection fraction (HFpEF), which often coexists with obesity or type 2 diabetes, mitochondrial dysfunction, insulin resistance, and lipid accumulation lead to metabolic reprogramming and metabolic inflammation." (PMID 40898242, 2025). "Visfatin was initially thought to act like insulin, and it regulates glucose metabolism and is elevated in obesity." (PMID 40013194, 2025). "POMC neurons signal satiety by activating melanocortin receptors, and their dysfunction leads to obesity and insulin resistance." (PMID 40864762, 2025). "A 38-year-old female with typical PCOS features presented with hypertension, obesity, and elevated fasting and postprandial insulin levels." (PMID 39896947, 2025). "Hormonal signaling via leptin, insulin, and ghrelin receptors in the olfactory bulb and mucosa also influences odor detection and processing, and such hormonal imbalances are common in obesity." (PMID 41010291, 2025). "When the pancreas is exposed to high amounts of lipid in obesity, impairment of autophagic flux and lysosomal function are found in the pancreatic β-cells, as well as reduced insulin secretion and cellular viability." (PMID 40366502, 2025). "Markers such as malondialdehyde (MDA) and oxidized LDL (Ox-LDL) are significantly elevated in obesity, indicating sustained oxidative damage to lipids and vascular tissues, which further impairs insulin signaling." (PMID 41334336, 2025). "Obesity-related metabolic alterations are primarily driven by adipokines and myokines, which regulate energy balance and insulin sensitivity through intricate signaling pathways, including autocrine, paracrine, and endocrine mechanisms." (PMID 40970779, 2025). "Taken together, TRZ, by regulating insulin sensitivity and obesity profile, reduces the detrimental effects of T2D and obesity on AD development." (PMID 40498212, 2025).
Obesity (continued). "It has been shown that long-term systemic treatment of AKG effectively lowered blood glucose levels, which were associated with decreased hepatic gluconeogenesis and increased insulin secretion, in diet-induced obesity and db/db mice." (PMID 41181587, 2025). "As previously suggested, these individuals also exhibit poorer insulin sensitivity compared to their peers with metabolically healthy obesity, findings that are partially supported by our results." (PMID 40808847, 2025). "Altered miRNA profiles in obesity directly feed back on metabolic targets, altering a number of nutrient sensing, adipogenic and insulin-signaling genes." (PMID 41228448, 2025). "There have also been observations in murine studies where there was a reduction in body weight and a shift toward improved insulin sensitivity following SCFA treatment in mice with high‐fat diet‐induced obesity." (PMID 40051343, 2025). "Approximately 10% to 20% of all individuals with obesity are metabolically healthy, with insulin sensitivity comparable to those of healthy, normal-weight individuals." (PMID 40862085, 2025). "AhR deficiency protects AhR−/− and AhR+/− mice from high-fat diet (HFD)-induced obesity, hepatic steatosis, insulin resistance, and inflammation, while preserving insulin signaling in major metabolic tissues." (PMID 41440753, 2025). "By transporting bioactive cargo, adiposomes are expected to influence peripheral insulin sensitivity, inflammatory signaling, and vascular homeostasis, thereby playing a potentially central role in the progression of obesity-related metabolic diseases." (PMID 40981199, 2025). "For instance, it has been shown that patients with obesity exhibit significant gene expression changes in genes involved in inflammation, lipid metabolism, and insulin signaling pathways." (PMID 40229590, 2025). "Elevated serum levels of leptin are frequently found in human obesity due to thehormone's degree of influence on hunger, energy consumption, adipose production and insulin function.Serum leptin levels increase with body mass index (BMI) or waist circumference." (PMID 40255297, 2025). "Obesity can impact systemic alteration of metabolites, inflammation, hormone secretion, insulin sensitivity, and expression of cytokines and chemokines." (PMID 40863244, 2025). "In skeletal muscle, GSK3 disrupts glucose metabolism through interference with insulin signaling and the inhibition of glycogen synthesis, contributing to muscle insulin resistance and impaired glucose utilization in obesity." (PMID 40218884, 2025). "In obesity, expanded adipose tissue becomes metabolically active, releasing pro-inflammatory cytokines, which interfere with insulin signaling pathways by promoting serine phosphorylation of insulin receptor substrate (IRS)." (PMID 39857741, 2025). "Chronically elevated insulin levels contribute to the maintenance of obesity by promoting lipogenesis in adipose tissue and inhibiting lipolysis." (PMID 41011232, 2025). "While these conditions have distinct clinical courses, obesity contributes to their pathogenesis through shared mechanisms, such as visceral adiposity, systemic inflammation, insulin resistance, and ectopic pancreatic fat deposition." (PMID 40732935, 2025). "The psPRS for Obesity from hard-clustering was significantly associated with a higher incidence of clinical requirement of insulin treatment (HR 1.09 [95% CI 1.05, 1.13], p= 9.3×10−6) and insulin initiation (HR 1.05 [95% CI 1.01, 1.08], p=0.0050)." (PMID 39531041, 2025). "Research has shown that anthocyanins can improve insulin secretion and alleviate obesity-related metabolic disorders." (PMID 40941257, 2025). "TAAR1 agonists have emerged as promising therapeutic agents capable of modulating glucose homeostasis, enhancing insulin secretion and suppressing appetite, making them attractive candidates for the treatment of obesity and related metabolic disorders." (PMID 41155326, 2025).
Obesity (continued). "Overall, the disturbed regulation of FOXO factors in obesity results in impaired metabolism, fat accumulation, and increased insulin resistance in organs, reflecting its critical role in obesity-related diseases." (PMID 40218884, 2025). "Berberine (BBR) is a natural isoquinoline alkaloid extracted from Coptis chinensis in traditional Chinese medicine, with the characteristics of anti-hyperglycemia, anti-obesity, anti-inflammation, and insulin resistance promotion." (PMID 39791173, 2025). "Overweight and obesity lead the ß cells of the pancreas to a secretory effort, as they are called to release a greater amount of insulin to maintain glucose levels within the physiological range." (PMID 38778593, 2025). "Clinical evidence confirms that dopaminergic drugs can improve the clinical manifestations of metabolic syndrome and obesity, substantially enhancing glucose–insulin metabolism and lipid profiles." (PMID 40464046, 2025). "Higher circulating myostatin independently predicts lower insulin sensitivity in adults with overweight or obesity, while reduced irisin levels accompany impaired glucose tolerance and lower aerobic capacity." (PMID 41515940, 2025). "As compared with individuals with normal weight, people with obesity exhibit higher postprandial glucose, insulin, TG, and inflammatory markers such as IL-6, TNF-α, and CRP." (PMID 41301434, 2025). "Insights from recent studies indicate that IP6K1 plays a pivotal role in regulating metabolic processes such as insulin secretion and obesity." (PMID 40573111, 2025). "For example, six weeks of exercise in hypoxic conditions (15% O2, 3 times per week for ~ 1 h) improved glucose tolerance and insulin levels in adolescents with obesity, as well as insulin sensitivity in men with obesity and metabolic syndrome." (PMID 39298040, 2025). "FXR, the primary BA receptor, modulates glucose homeostasis by enhancing insulin sensitivity and inhibiting hepatic gluconeogenesis, thereby mitigating obesity." (PMID 41305647, 2025). "Outside the liver, hepatic Rspo3 induction ameliorated reduced skeletal muscle quality in obesity by restoring insulin signaling and up-regulating muscle PPARα expression and muscle fatty acid utilization." (PMID 39854351, 2025). "The requirement for higher EMO doses (200–400 mg kg−1 day−1) in the severely insulin-resistant ob/ob model aligns with previous reports in diet-induced obesity models." (PMID 41471299, 2025). "Medications need to be chosen considering insulin secretion and insulin resistance, age, degree of obesity, severity of chronic complications, liver function, and kidney function." (PMID 40456113, 2025). "In sarcopenic obesity, adipose tissue‐resident macrophages can foster a sterile inflammatory milieu, potentially dampening insulin signaling." (PMID 39764565, 2025). "Another critical consequence of unhealthy WAT in obesity is insulin resistance and elevated insulin levels in the circulation." (PMID 39496581, 2025). "When comparing changes across MDS tertiles, insulin and HDL-C exhibited significant differences, and the reduction in insulin levels in participants with obesity remained statistically significant compared with those in the BMI < 25 kg/m2 group." (PMID 41228493, 2025). "This increased insulin requirement can create a cycle whereby insulin therapy promotes further weight gain, exacerbating obesity and further complicating glucose management." (PMID 40553147, 2025). "Inhibition of intestinal FXR has been shown to have beneficial impacts on insulin sensitivity in animal models of obesity." (PMID 40666326, 2025). "Diet-induced obesity leads to increased circulating free fatty acids, insulin, and glucose that trigger “low-grade” inflammation that is causally related to inflammatory macrophage expansion within the hypertrophic adipose tissue." (PMID 39532538, 2025).
Obesity (continued). "Beyond energy balance, obesity features chronic low-grade inflammation and metabolic endotoxemia that together impair insulin sensitivity and cardiometabolic health." (PMID 41036194, 2025). "With the progression of obesity, immune cells including macrophages and neutrophils infiltrate insulin-sensitive tissues such as white adipose tissue (WAT), the liver, and skeletal muscle." (PMID 40697664, 2025). "It has a pivotal role in the regulation of glucose metabolism, lipid homeostasis, and insulin sensitivity, which makes it of special interest for the study of obesity and metabolic diseases such as T2D and cardiovascular diseases." (PMID 40218884, 2025). "Studies have shown that during the development of obesity, the number of B cells increases within adipose tissue and their absence leads to improved glucose tolerance and insulin sensitivity." (PMID 40662198, 2025). "Mice and rats have been extensively utilized to examine the impacts of A. muciniphila on obesity, insulin resistance, immunity, gut physiology, and gut microbiota composition." (PMID 39940420, 2025). "This distinction is crucial because when HIIT and MICT are matched for energy expenditure, their metabolic effects on individuals with overweight or obesity, such as reductions in intrahepatic fat levels and circulating insulin, tend to be comparable." (PMID 40427653, 2025). "The rise in Oscillospira, a genus inversely associated with obesity and inflammation, aligns with DIO’s reported anti-hyperglycemic effects, possibly mediated through improved insulin sensitivity and reduced adipose tissue inflammation." (PMID 40458807, 2025). "Obesity is a well-documented risk factor for DFU development and poor healing outcomes, as it contributes to chronic inflammation, insulin resistance, and increased mechanical stress on the lower extremities." (PMID 40278312, 2025). "Critically, timed low-dose STZ after HFD yields a reproducible window for IR onset, allowing side-by-side interrogation of obesity (HFD-only) versus insulin-resistant (HFD + STZ) states in the same genetic background." (PMID 41002949, 2025). "These foods have been shown to significantly influence the metabolic processes associated with obesity and T2DM by improving insulin sensitivity, regulating blood sugar levels, and modulating fat metabolism." (PMID 40004938, 2025). "Butyrate supplementation for an extended period in mice prevents diet-induced obesity and improves markers like insulin sensitivity and lipid profiles by enhancing fatty acid oxidation and increasing sympathetic outflow to BAT." (PMID 40183584, 2025). "Mutations or deficiency of TLR4 have been shown to confer partial protection against the metabolic consequences of obesity, mitigating insulin resistance and systemic inflammation." (PMID 41226745, 2025). "On the other hand, the sensitivity to insulin is largely affected by adipose tissue metabolic function and interactive biologic processes, which are found to be abnormal in obesity." (PMID 41210503, 2025). "Obesity exacerbates MAFLD and osteoporosis by causing chronic low-grade inflammation in the liver, increasing insulin resistance, affecting leptin and lipocalin secretion, and disrupting intestinal microcirculation." (PMID 40547375, 2025). "Overall, this can be attributed to the inability of insulin to bind to insulin receptors or due to disruptions in the signal transduction pathway when insulin is bound and is often a consequence of obesity." (PMID 40052519, 2025). "In another study, plasma visfatin levels and visfatin mRNA expression were measured in 189 adults with a wide range of obesity, body fat distribution, insulin sensitivity, and glucose tolerance." (PMID 41227378, 2025). "Socs3 is upregulated in obesity and inhibits leptin and insulin signaling, while its downregulation reduces hepatic lipid levels in obese Sprague–Dawley rats." (PMID 40535017, 2025).